E2F1 (E2F transcription factor 1)
Diseases named in the same sentence as E2F1 in open-access papers (continued):
Sharing a sentence is not in itself a finding about the gene and the disease.
cancer (continued). "We demonstrated the inhibition of COX-2 expression after cyD1 and E2F1 silencing, substantiating other studies indicating a correlation between COX-2 and cyclins in cancer." (PMID 30050877, 2017). "The NFYB/E2F1 complex becomes connected with FOXO1/3 and is the factor of the FOXO- dependent signaling cascade, which is activated in the cells of different cancers." (PMID 28031533, 2017). "In the presence of higher levels of miR-302b, reduced levels of E2F1 result in the partial abrogation of ATM activation, affecting cancer cell ability to repair DNA and proliferate." (PMID 26623722, 2016). "Inactivation of these tumor suppressor genes or activation of oncogenes such as E2F1, c-Myc, and STAT5 in pre-cancer and cancer cells enhance SIRT1 expression." (PMID 27708228, 2016). "Members of the miR-17–92 cluster targeted numerous cancer suppressor genes, e.g. Pten, BIM, E2F1, p21 and STAT3, showing functions in differentiation and apoptosis." (PMID 25647305, 2015). "Although Pontin and Reptin have other binding partners that are relevant for cancer progression such as β-catenin and Myc31, 37, our results, combined with the frequent aberrant E2f activity in cancer, suggest that their recruitment by E2f1 may be a common mechanism to drive cancer progression." (PMID 26639898, 2015). "Thus, this outcome to seem of contradiction hinted that e2f-1 might be a key transcription factor which stimulated the conversion from normal cells to cancer cells; therefore, it might be why its expression was markedly lower in the later periods of progression of GC." (PMID 24393368, 2014). "Accordingly, overexpression of CCND2, E2F1 and E2F2 were reported in various cancer types, including OS." (PMID 25174983, 2014). "In summary, we demonstrated here that cancer cells transfected XIAP deletion of RING domain led to cyclin e transcription and protein expression via binding with and modulation of the E2F1 transactivation." (PMID 25216527, 2014). "Increased E2F1 activity or inactivation of pRB therefore maintains high PDK4 expression and constitutively suppresses glucose oxidation, such as observed in cancer." (PMID 23355973, 2013). "It is noticed that in non-cancer cell lines HEK293 (human embryonic kidney cell), HMEC (human mammary epithelial cell) and HaVSMC (human aortic vascular smooth muscle cell), E2F1 levels are low and correspondingly, h-eag1 level is also low in these cells." (PMID 21655246, 2011). "We confirmed the down-regulation of E2F1 and E2F2 expression in three different cancer cell lines, SW780, A549 and SBC5 treated with siRNAs, by quantitative real-time PCR." (PMID 20226085, 2010). "The mir-17-92 cluster is highly expressed in carcinoma in situ (CIS) testis and inhibits apoptosis by translationally down-regulating E2F transcription factor 1(E2F1) in CIS cells." (PMID 19210773, 2009).
cancer (continued). "Comparison of the mouse skin pRb/p107/p130 signature mapped to human genes with Signature 5 of mucosal HPV-carcinomas revealed a significant overlap of 7 genes: DHFR, E2F1, LIG1, MCM2, PCNA, RFC4, TYMS and USP1." (PMID 19721808, 2009). "For the first time, we are able to identify in cancer microarray data significant indirect effects of transcription factors, such as PPAR proteins, E2F1 and MYC, on survival." (PMID 18358079, 2008). "Many of the transcription factors with indirect effects, including PPARG, E2F1, STAT5A, and MYC, have been suggested as targets for cancer therapy." (PMID 18358079, 2008). "To directly assess the role of cellular proteins involved in the G1/S transition on TS expression, we over-expressed E2F1, Dp1 and cyclin E in human HCT116 and MCF-7 cancer cell lines as well as in GM38 normal fibroblasts." (PMID 17923872, 2007). "All 33 cancer cell lines tested possessed distinct E2F1 activity, but five normal growing cell lines did not." (PMID 41511373, 2026). "Here, this study focused on probing the functions of E2F1 and EXOSC10 on HCC growth and cancer stemness, moreover, their interaction in HCC progression were further investigated, which may provide a novel insight into the therapy of HCC." (PMID 40221814, 2025). "Therefore, the Rb/E2F1 axis is likely involved in the transcriptional induction of NAA40 in normal proliferating and cancer cells." (PMID 38864963, 2025). "Overexpressing c-Myc and E2F1 reduces the effectiveness of FB23 and ibrutinib in treating cancer." (PMID 41281757, 2025). "In this study, we demonstrated that the cancer cell specificity of ERE73 (1 + 2)-ARF (−13) and ERE73 (3 + 4)-ARF (−13) promoter constructs is significantly greater than that of the native ARF promoter and the commonly used E2F1 and hTERT promoters." (PMID 41439972, 2025). "Notably, among the 14 TFs whose binding sites were sex-dependently enriched across different cancers, eight were previously found to be enriched among sex-biased expressed genes, including SP1, ETV1, ELF1, E2F1, CREB1, CTCF, SIX2, and SOX2." (PMID 39716176, 2024). "Similarly, our study also predicts target genes like E2F1, WNT1, RALA, and PTEN that reveal their involvement in cancer progression." (PMID 38741808, 2024). "In addition, in two human cancer cell lines (U2O and HeLa), E2F7 recruited the corepressor C-terminal binding protein to repress the transcription of E2F1 in a C-terminal binding protein-dependent manner, leading to reduced cell proliferation." (PMID 39613162, 2024). "The upregulated DEGs showed various enforced transcription factors’ networks including IRF3, TAL1, JUN, and FOXA, whereas the downregulated DEGs demonstrated dramatic network suppression of E2F1, a cell cycle progressor, and NR2C2, a cancer-promoting orphan receptor." (PMID 37612293, 2023). "Indeed, E2F1 silencing completely abrogates the induction of TSPYL2 expression in response to etoposide in different normal and cancer male and female cell lines." (PMID 36918555, 2023). "Furthermore, pan-cancer analysis revealed a significant positive correlation between MAD2L2 and E2F-1 expression across multiple cancer types." (PMID 38017538, 2023).
cancer (continued). "Considering that appropriate downregulation of E2F1 is critical to maintaining genomic stability, blocking this process allows the inhibition of cancer cell growth, thus suggesting a critical role of APC/CCDH1 in DNA damage and cancer." (PMID 37176148, 2023). "Several ARGs showed gain of CNVs such as E2F1, MCL1, and PIK3CA across multiple cancers." (PMID 36937870, 2023). "Mechanically, the RAS/RAF/MEK/ERK signaling pathway upregulates the expression of E2F transcription factor 1 (E2F1), which binds to the promoter of KLF4, thereby increasing the expression of KLF4 at the protein and mRNA levels and reducing the apoptosis of cancer tissues." (PMID 36761967, 2023). "Considering the analysis results of the transcriptional data of various cancers in the TCGA database, it is suggested that UBE2C may be a downstream gene that is co-regulated by KAT2A and E2F1." (PMID 36292703, 2022). "Increased E2F1 and FOXM1 in cancers with high levels of TRPM2 may contribute to transcriptionally increased expression of α1, β1 and β5 integrins, and greater migration and invasion." (PMID 36446940, 2022). "Consistent with cohort 1, no significant changes in expression levels of the cancer progression E2F1-miRNA network members miRNA-17-5p, miRNA-106a, miRNA-106b were seen between the groups." (PMID 36231008, 2022). "Pathway enrichment analysis (KOBAS 3.0) of the genes in the MEbrown module showed that RECK and E2F1 were enriched in the miRNA in cancer pathway (p < 0.05), with no significant enrichment detected for the other genes." (PMID 35123404, 2022). "Moreover, eight axes (e.g., OIP5-AS1/miR-124-5p/IDH2) are involved in key pathways, such as Wnt/b-catenin, E2F1, TGF-β, SMAD, ERK/MAPK, HIF-1α, Notch, PI3K/Akt signaling, and cancer cell stemness." (PMID 36362406, 2022). "Moreover, eight axes are involved in key pathways: Wnt/b-catenin, E2F1, TGF-β, SMAD, ERK/MAPK, HIF-1α, Notch, PI3K/Akt signaling, and cancer cell stemness." (PMID 36362406, 2022). "By screening the transcriptome data of 11 cancer tissues of TCGA, it was exposed that the gene set potentially co-regulated by KAT2A and E2F1 was significantly enriched in the cell cycle, and participated in DNA replication, base excision repair, and nucleotide excision repair." (PMID 36292703, 2022). "In addition, the expression levels of KAT2A and E2F1 in pathological stages were remarkably higher expressed in stage III and IV in 10 cancers." (PMID 36292703, 2022). "To examine if the E2F1 and p65 cistromes are shared between cell types and whether they exhibit universal characteristics we analysed E2F1 and p65 ChIP-seq datasets from U2OS cancer cells." (PMID 36291831, 2022). "Given the results of our immune infiltration analysis, we propose that E2F1, E2F2, E2F3, and E2F5 may potentially affect the progression of cancer through anticancer immunity." (PMID 35531101, 2022). "Besides, NRF1 up-regulated E2F1 expression transcriptionally, then orchestrated both c-MYC and E2F to regulate their target genes for cancer proliferation." (PMID 35448958, 2022). "Importantly, with the discovery of a large number of E2F1:coregulator complexes that drive metastasis, patient-specific pharmacogenomics profiling of cofactors combined with small molecule inhibitors identified using pharmacophore modeling approaches may improve personalized cancer therapy." (PMID 36678712, 2022). "This study revealed the common characteristics of KAT2A/E2F1/UBE2C and clarified the mechanism of this axis across pan-cancer through RNA-seq dada and in vitro experiments, which might shed light on pan-cancer treatment." (PMID 36292703, 2022).
cancer (continued). "Overall, members of the cancer progression E2F1–miRNA network (miRNA-17-5p and 106a/b clusters, miRNA-15a/b, miRNA-16, miRNA-34a, miRNA-205, and miRNAs-449a/b/c) were absent from the identified set of VAT miRNAs altered according to E2F1 expression." (PMID 36231008, 2022). "Saleembhasha and Mishra 32, first published in 2017 working with a TCGA RNA-seq dataset of 5601 samples from 15 different primary cancer types, proposed a pan-cancer regulatory axis consisting of PVT1, E2F1 and FOXM1 as common gene expression regulatory entity." (PMID 35534592, 2022). "In summation, in this study we have identified an lncRNA EMSLR that maintains the invasive properties of cancer cells and our work exemplifies how C-MYC and E2F1 signal transduction pathways control the network of lncRNA genes to modulate cell proliferation and differentiation." (PMID 35169159, 2022). "The most studied cancer-related processes regulated by SETD7 were cell proliferation, apoptosis, epithelial-mesenchymal transition, migration and invasion with special relevance to the pRb/E2F-1 pathway." (PMID 35326563, 2022). "Hitherto, no conclusive study has reported the role of KAT2A and E2F1 interactions in the pan-cancer landscape." (PMID 36292703, 2022). "Different from the finding in NUT carcinoma cells, however, we provide evidence that E2F1 knockdown had little or no obvious effect on the BET inhibitor sensitivity in both RB WT and deficient PCa cells." (PMID 36274096, 2022). "Furthermore, the overexpression of E2F transcription factor 1 (E2F1), Enhancer of Zeste Homolog 2 (EZH2), and SUZ12 genes have been correlated with progression, migration and invasiveness of cancer." (PMID 34094648, 2021). "Different from cancer cells, we did not observe the enrichment of either E2F1 or MYC at this region in normal RWPE1 cells, whereas MYC showed obvious enrichment at this SNP containing region when the cells were treated with DHT." (PMID 34858826, 2021). "Moreover, FTO influences the progression of cancer by regulating multiple signaling pathways, such as FTO-PGC-1 α signaling axis, mediating PKM2 demethylation, impairing the translation efficiency of E2F1 and Myc." (PMID 33692753, 2021). "Specifically, ESR1 and E2F1 were not correlated in the group with favorable prognosis, while they were significantly positively correlated in recurrent cancer." (PMID 33852600, 2021). "Notably, BCL2L1, E2F1, HRAS, MAPK8, MITF, RELA, and SP1 were found in both mitophagy and cancer pathways." (PMID 34262589, 2021). "Moreover, SNHG12 was also reported to be involved in the tumorigenesis of other cancers by interacting with miR-129-5p/WWP1, miR-195/CCNE1, miR-125-5p/MDM4, miR-326/E2F1, and miR-15a-5p/SALL4 axes." (PMID 33294456, 2020). "As cancer cells with elevated E2F1 activity have been shown to be sensitive to HDAC inhibitor‐induced cell death and RB1 inactivation in RB results in deregulated E2F1 activity, several studies have investigated the effects of HDAC inhibitors on RB cell death." (PMID 31782885, 2020). "E2F1 and FOXM1 are two well-studied genes involved in cancer." (PMID 33396205, 2020). "This feedback is abrogated in cancer cells lacking p14Arf, resulting in a constitutive activation of E2F1 in cells experiencing high protein expression and mRNA translation stress." (PMID 32453417, 2020). "The key findings are that through E2F1, FOXM1 and PVT1 regulatory axis and possible interactions with different coding genes, PVT1 may be playing a prominent role in pan-cancer development and progression." (PMID 30809433, 2019). "Although E2F1 is known as a master regulator of cell proliferation, there is emerging evidence that its role is only visible in cancer cells and not in normal cell cycling." (PMID 31384395, 2019). "We found that the ‘high E2F1/APLF/DCLRE1C’ signature does not produce significantly different outcomes across multiple cancer types, but instead it is highly specific for BC." (PMID 31287003, 2019).
cancer (continued). "The dedifferentiation of cancer cell was inhibited through inhibition of IL-6, CCAAT/enhancer binding protein alpha (CEBPα), Spi-1 proto-oncogene (PU.1), c-Myc and E2F transcription factor 1 (E2F1)." (PMID 30373594, 2018). "Identification of PARP‐1 as a regulator of E2F1 transcriptional function in PCa, specifically with regard to regulation of HR gene expression, sheds new light as to the molecular impact of PARP‐1 function in cancer." (PMID 30467127, 2018). "We identified consistently upregulated genes (such as E2F1, EZH2, FOXM1, MYBL2, PLK1, TTK, AURKA/B and BUB1) and consistently downregulated genes (such as SCARA5, MYOM1, NKAPL, PEG3, USP2, SLC5A7 and HMGCLL1) across various cancers." (PMID 28427185, 2017). "Furthermore, four key genes highly involved in ‘pathways in cancer,’ BIRC5, E2F1, CCNE1 and CDKN2A, were bioinformatically validated and selected out for further diagnostic and prognostic tests." (PMID 28316892, 2017). "The increased expression of E2F1 transcription factor can alter TGF-ß mediated growth inhibitory effects by inducing cell cycle arrest and apoptosis as a result of liver and kidney injury but also contributes to cancer development." (PMID 29296203, 2017). "E2F1 appeared many times in common L-FFL motifs and therefore might play different roles in different types of cancers by interacting with different lncRNAs and miRNAs." (PMID 27322142, 2016). "Unlike its well documented roles in regulating cell-cycle progression, cell differentiation, DNA repair, and apoptosis, the role of E2F1 in promoting cancer cell aerobic glycolysis has not been reported before." (PMID 25816777, 2015). "Binding that was induced in cancer, but not in the normal tissues, was displayed by the transcription factors E2F1, AP3, LIII-BP, PAX6, ADD-1, and CCAC." (PMID 25861239, 2015). "We hypothesize that the oncogenic role of E2F1 can also be attributed to its promotion of glycolysis through suppressing SIRT6 expression and activity in cancer cells." (PMID 25816777, 2015). "The significant down-regulation of cyclin B, cyclin D1, E2F1, survivin, and c-MYC in human RCC cells mediated by ART may be sufficient to arrest cell cycle progression and to suppress cancer stemness." (PMID 26426994, 2015). "Reported targets of miR-330-3p in various cancer types include Sp1, CDC42 and E2F1." (PMID 26221725, 2015). "Similarly, BRCA1 and CHEK2 were suggested to participate in cancer development by modulating DNA repair and cell cycle checkpoints in collaboration with FOXM1 and E2F1, respectively." (PMID 26001967, 2015). "Previous studies reported that E2F1 could affect cell proliferation and apoptosis and that E2F1 may be involved in regulating MDR in some cancers." (PMID 25466554, 2014). "Moreover, knocking down EZH2 expression suppresses the cell invasion by downregulating E2F1 and MMP9 in endometrial and in colorectal cancer." (PMID 25295088, 2014). "Taken together with poor clinical outcome of the cancer patients with high expression of XIAP in nuclear, our novel findings of XIAPΔRING in nuclear location and upregulation of E2F1/Cyclin E axis provide us significant insight into understanding of nuclear XIAP in cancer patients." (PMID 25216527, 2014). "Indeed, overexpression of E2F1 is observed in CRC cells, suggesting its tumorigenic role in the cancer." (PMID 24465681, 2014). "In addition, transcription factors E2F1 and ESR1 are involved in the signaling pathways, which are important transcription factors and therapeutic targets in different types of cancer, including BC." (PMID 24040069, 2013).